ROBO2 (roundabout guidance receptor 2)
Diseases named in the same sentence as ROBO2 in open-access papers (continued):
Sharing a sentence is not in itself a finding about the gene and the disease.
microtia (3 papers, 2024 to 2025). "Scholars have also found that mutations located between ROBO1 and ROBO2 increase the risk of microtia in American indigenous populations." (PMID 40809693, 2025). "Genetic studies have shown that microtia is linked to mutations in ROBO1/ROBO2, HOXA2, SIX1/SIX5, TBX1, or CHUK in humans." (PMID 38690987, 2024). "A recent study uncovered a minimal microtia locus that carries a polymorphic repeat element, which may disrupt ROBO1 and ROBO2 gene expression in the auricle and be responsible for the high incidence of microtia in East Asian and Amerindian populations." (PMID 38690987, 2024).
pancreatitis (3 papers, 2018 to 2021). Inflammation of the pancreas. "In vivo, the Robo2-deficient mice exhibited TGFβ-dependent increased fibroblast activation, fibrosis and immune signalling markers in response to experimental pancreatitis, while in PDAC patients, low ROBO2 expression high ROBO1 expression were associated with poorer survival." (PMID 34638468, 2021). "To determine whether inhibition of the TGF-β pathway in vivo could inhibit Robo2-mediated stromal effects observed after pancreatitis, we administered galunisertib during the caerulein treatment." (PMID 30504844, 2018). "A previous study on pancreatitis and PDAC mouse models showed that Robo2 can act as a stroma suppressor gene by restraining myofibroblast activation and T-cell infiltration." (PMID 34503185, 2021). "Here we report that in pancreatitis and PDAC mouse models, epithelial Robo2 expression is lost while Robo1 expression becomes most prominent in the stroma." (PMID 30504844, 2018).
vesicoureteral reflux (3 papers, 2011 to 2020). Abnormal flow of urine from the urinary bladder back into the ureters. "Disruption of ROBO2 in humans causes vesicoureteral reflux (VUR)/congenital anomalies of the kidney and urinary tract (CAKUT)." (PMID 27460642, 2016). "ROBO2 is one of at least twenty genes implicated in non-syndromic vesicoureteric reflux (VUR), though the majority of genetic aetiology of VUR is still unknown." (PMID 32041992, 2020). "ROBO2 gene disruption causes vesicoureteric reflux (VUR) amongst other congenital anomalies." (PMID 32041992, 2020).
asthma (2 papers, 2021 to 2024). "The association of ROBO2 was validated at genomic-region level, by analyzing asthma exacerbations despite ICS use in Europeans." (PMID 34442380, 2021). "Larger studies coupled with functional evaluation are required to fully understand the role of ROBO2 in responsiveness to ICS in patients with asthma." (PMID 34442380, 2021). "detected decreased levels of ROBO2 and SLIT2 in chronic obstructive pulmonary disease (COPD) patients, a disease with underlying mechanisms shared with asthma." (PMID 34442380, 2021). "The findings of this study suggest the potential implication of ROBO2 in the response to asthma treatment with ICS specifically in European populations, with a lack of evidence of replication in Latinos/Hispanics and African Americans." (PMID 34442380, 2021). "Taken together with the biologically plausible role of ROBO2 in pulmonary and immune functions, ROBO2 potentially represents a novel locus determining the response to ICS in patients with asthma." (PMID 34442380, 2021). "Furthermore, ROBO2 has been evidenced to be an important factor in triggering airways constriction in asthma and COPD." (PMID 34442380, 2021). "Altogether, this evidence suggests that ROBO2 could play an important role in asthma phenotypes, including the response to ICS in asthma." (PMID 34442380, 2021).
cardiomyopathy (2 papers, 2013 to 2025). A disease of the heart muscle or myocardium proper. "Similarly, ‘GG’ genotype of rs17736312 in ROBO2 has been reported to be significantly associated with anthracycline-induced cardiomyopathy in survivors of childhood cancers." (PMID 40382596, 2025). "Distinct isoforms for ROBO2 are reported and alternative splicing of ROBO1 has been shown in response to hypoxia in endothelial cells, albeit not in context of cardiomyopathy." (PMID 40382596, 2025).
colon cancer (2 papers, 2015 to 2023). "Of the genes listed in Results—with inserts in exons or almost in exons, or with multiple inserts—ROBO2 is a candidate tumour suppressor, and is a target of insertions in colon tumours." (PMID 26159513, 2015). "In a study of primary colon cancer, genes such as IGBP3, OAS2, MX1, and Robo2 were found as prognostic markers in an independent series of colon cancer patients." (PMID 36759842, 2023).
congenital diaphragmatic hernia (2 papers, 2020 to 2024). A posterolateral defect of the diaphragm that allows passage of abdominal viscera into the thorax, leading to respiratory insufficiency and persistent pulmonary hypertension with high mortality. "In a mouse model of congenital diaphragmatic hernia with genetic ablation of Robo1 and Robo2, PNEC product secretion was increased, which led to increased infiltration of macrophages and other immune cells into the lung." (PMID 38813849, 2024).
depression (2 papers, 2023 to 2024). "Multiple identified genes, such as RNASEL, RGS16, RFX4 and ROBO2 were reported to be associated with chronotype, depression or cognition in previous studies." (PMID 38778419, 2024). "There are also a few genes with suggestive evidence in multiple analyses, such as ROBO2, which had suggestive evidence associated with SD (p = 6.21 × 10−5 before adjusting with depression, p = 1.58 × 10−4 after adjusting with depression, p = 1.46 × 10−4 after conditioning on SA)." (PMID 36253440, 2023). "Thus, RFX4, RGS16, RNASEL and ROBO2 may be the important genetic factors indirectly linked to sleep disturbances and depression via circadian rhythm or neurotransmitters." (PMID 38778419, 2024). "We identified several candidate genes for sleep disorders in the subjects with depression, such as RFX4, RGS16 and ROBO2." (PMID 38778419, 2024).
diabetes (2 papers, 2011 to 2021). "Robo βKO mice, in which the genes Robo1 and Robo2 are deleted selectively in β cells, provide a unique model of altered islet spatial architecture without loss of β cell differentiation or islet damage from diabetes." (PMID 34231467, 2021).
kidney stone (2 papers, 2021 to 2024). "Moreover, the elevated expression of ceRNAs such as NEAT1, PVT1, hsa-miR-23b-3p, hsa-miR-429, hsa-miR-139-5p, CCL7, and ROBO2, along with the presence of infiltrating immune cells like Mps and mast cells, may be associated with the development of kidney stones." (PMID 38397450, 2024). "The results indicated that significant expressions of ceRNAs (NEAT1, PVT1, hsa-miR23b-3p, hsa-miR-429, hsa-miR-139-5p, CCL7, and ROBO2) and infiltrating immune cells (Mps and mast cells) may be involved in the pathogenesis of kidney stones." (PMID 38397450, 2024).
lung carcinoma (2 papers, 2019 to 2024). "In the present study, we observed that Slit2 and Robo2 mRNAs are decreased in lung cancer samples when compared to normal tissue." (PMID 31921388, 2019). "Thus, we suggest that decreased expression of Slit2 and Robo2 genes in lung cancer may favor the migration of Schwann cells; consequently, favoring invasion by neoplastic tissue." (PMID 31921388, 2019). "In the lung carcinoma cell line NCI-H2087, miR-25 is overexpressed and maintains slightly elevated levels of ROBO2, which indicates that the overexpression of miR-25 must be above the values reported in NCI-H2087 to be able to down-regulate ROBO2 expression." (PMID 38612763, 2024).
pancreatic ductal adenocarcinoma (2 papers, 2017 to 2021). An infiltrating adenocarcinoma that arises from the epithelial cells of the pancreas. "ROBO2 participates as axon guidance, and cell migration and low levels of mRNA expression are associated with poor survival in pancreatic ductal adenocarcinoma." (PMID 33810183, 2021).
acute lymphoblastic leukemia (1 paper, 2018). Leukemia with an acute onset, characterized by the presence of lymphoblasts in the bone marrow and the peripheral blood. "Mutations of CREBBP are frequently found in acute lymphoblastic leukemia or diffuse large B‐cell lymphoma, and mutant‐ROBO2 is detected in patient of MDS." (PMID 29769258, 2018).
acute myeloid leukemia (1 paper, 2019). Acute myeloid leukemia (AML) is a group of neoplasms arising from precursor cells committed to the myeloid cell-line differentiation. "Acute myeloid leukemia patients were generally high expressers of ROBO1 and ROBO2 compared to the controls (p < 0.0001, p < 0.001, respectively)." (PMID 30820596, 2019).
aortic regurgitation (1 paper, 2023). "In regards to BAV adult patients with variants in ROBO1, ROBO2, SLIT1 and SLIT3 genes, the presence of BAV-related complications such as aortic regurgitation, aortic stenosis, and AscAA was checked." (PMID 36855159, 2023).
cervical tumors (1 paper, 2012). "The alteration frequencies of ROBO1 and ROBO2 increased significantly from CIN to stage I/II tumors, indicating that these receptors were inactivated during the development of early invasive cervical tumors." (PMID 22719878, 2012).
chronic pancreatitis (1 paper, 2018). A chronic inflammatory process causing damage and fibrosis of the pancreatic parenchyma. "Our experiments with concomitant embryonic inactivation of Robo2 and mutant Kras activation (KC_Robo2F/F) followed by chronic pancreatitis show no additional phenotypic changes compared to controls." (PMID 30504844, 2018).
congenital hydronephrosis (1 paper, 2011). Congenital hydronephrosis is a renal urinary disease characterized by distension and dilation of the renal pelvis and calyces secondary to various congenital obstructive malformations of the kidneys and urinary tract that can evolve to renal atrophy. "Our data provide strong evidence that Robo2 is critical for maintaining both active and passive anti-reflux mechanisms and loss of Robo2 gene could cause progressive congenital hydronephrosis and high-grade dilating VUR with little chance of spontaneous resolution after birth." (PMID 21949750, 2011).
coronary artery disease (1 paper, 2021). "In past studies, circ_0124644 [derived from roundabout guidance receptor 2 (ROBO2) gene] had been reported to be highly expressed in the serum of coronary artery disease patients and was positively correlated with disease degree." (PMID 34249089, 2021).
COVID-19 (1 paper, 2022). A disease caused by infection with severe acute respiratory syndrome coronavirus 2. "Furthermore, plasma IL-8, IL-6, TNFRSF11B, and CSF EZR levels were allied to severe COVID-19 using the ordinal backward and best linear model, whereas plasma 4E-BP1 and CSF levels of PD-L1, BMP-4, CLEC10A and ROBO2 withstanded using one model only." (PMID 36351919, 2022).
diabetic nephropathy (1 paper, 2010). "In accordance with these results are our findings of decreased levels of ROBO2 mRNA in human diabetic nephropathy and focal segmental glomerulosclerosis." (PMID 20634963, 2010). "In diabetic nephropathy, a prevalent glomerulopathy, differential regulation of glomerular ROBO2 mRNA was found." (PMID 20634963, 2010).
emphysema (1 paper, 2025). "Of these, protein FAM177A1 and adiponectin demonstrated the strongest positive associations with percent emphysema, while ROBO2 and WAP four-disulfide core domain protein 1 (WFDC1) demonstrated the strongest inverse associations." (PMID 40616090, 2025).
endometriosis (1 paper, 2015). The growth of functional endometrial tissue in anatomic sites outside the uterine body. "With regard to their function, KCCN1 and ROBO2 are good candidate genes for endometriosis, since neoneurogenesis frequently occurs in endometriosis." (PMID 25722978, 2015).
Ewing sarcoma (1 paper, 2022). A small round cell tumor that lacks morphologic, immunohistochemical, and electron microscopic evidence of neuroectodermal differentiation. "Silencing of Slit2 receptors, Robo1 and Robo2, inhibited Ewing sarcoma growth as well." (PMID 36533189, 2022).
Fanconi anemia (1 paper, 2020). Fanconi anemia (FA) is a hereditary DNA repair disorder characterized by progressive pancytopenia with bone marrow failure, variable congenital malformations and predisposition to develop hematological or solid tumors. "Common gene copy losses represented by both models with HNC patient relevance are Robo2, an important candidate tumor suppressor of the ROBO–SLIT pathway (16qC3), and Fancb gene (XqF5, human FANCB) involved in the Fanconi anemia (FA) pathway, which is altered in subsets of HNC patients." (PMID 33053752, 2020).
gestational diabetes (1 paper, 2025). Carbohydrate intolerance first diagnosed during pregnancy. "This aligns with studies indicating that altered MAPK/ERK signaling is involved in CAKUT formation, with alterations caused by gestational diabetes and Gen1 and Robo2, which affect urinary tract development." (PMID 40563451, 2025).
gout (1 paper, 2023). A condition characterized by painful swelling of the joints, which is caused by deposition of urate crystals. "Regarding this urinary reflux, mutations in the ROBO2 are thought to be a potential genetic factor in patients with hyperuricemia and gout." (PMID 38060535, 2023).
hepatoma (1 paper, 2024). "Robo2 deficiency inhibits EMT and proliferation of hepatoma cells and augments the cell apoptosis by regulating YB-1, thus inhibits the occurrence of HCC and provides a new strategy for the treatment of HCC." (PMID 38297025, 2024). "Then we established HepG2 and Huh7 hepatoma cell lines with knock-down Robo2 by transfection with lentiviral vectors, and examined the occurrence of EMT, proliferation and apoptosis abilities in HCC cells by western blot, flow cytometry, wound healing assay and TUNEL staining." (PMID 38297025, 2024). "Meanwhile, we detected the apoptosis in the hepatoma cells, TUNEL staining showed that knock-down Robo2 could increase the apoptosis, while over-expression of YB-1 could counteract the upsurge of apoptosis caused by down-regulation of Robo2." (PMID 38297025, 2024). "After successfully constructing hepatoma cells with knock-down Robo2, it was confirmed that down-regulated Robo2 suppressed EMT and proliferation of hepatoma cells, and accelerated the cell apoptosis." (PMID 38297025, 2024). "In this study, we found that the expression level of Robo2 in human HCC tissues was significantly higher than that in normal liver tissues adjacent to cancer, and down-regulation of Robo2 could suppress the EMT and proliferation of hepatoma cells and stimulate the apoptosis of HepG2 and Huh7 cells." (PMID 38297025, 2024).
hydronephrosis (1 paper, 2011). Collection of urine in the renal pelvis that results in dilatation of the renal pelvis and calyces. "By ultrasound-guided percutaneous aspiration, we determined that unilateral hydronephrosis in Robo2-deficient mice was exacerbated by the retrograde flow of urine from the contralateral functional kidney through an enlarged ureterovesical junction." (PMID 21949750, 2011). "This procedure enabled us to follow the antenatal hydronephrosis progression noninvasively in the same Robo2-deficient mouse from embryo to neonate, a period with major physiological and functional changes during kidney and urinary tract development." (PMID 21949750, 2011). "In order to study the natural history of antenatal hydronephrosis in Robo2-deficient mice, we first established a noninvasive method to evaluate renal collecting system in mouse embryos." (PMID 21949750, 2011). "Here we used noninvasive high-resolution micro-ultrasonography and pathological analysis to follow the progression of antenatal hydronephrosis in individual Robo2-deficient mice from embryo to adulthood." (PMID 21949750, 2011). "Further developmental studies revealed early congenital dilatation of the ureteral orifice in Robo2-deficient mice with antenatal hydronephrosis and VUR." (PMID 21949750, 2011). "In the study reported here, we used noninvasive micro-ultrasonography and pathological analysis to determine the natural history of antenatal hydronephrosis in individual Robo2-deficient mice from embryo to adulthood." (PMID 21949750, 2011). "Our results showed that loss of Robo2 gene could cause progressive congenital hydronephrosis and high-grade dilating VUR with little chance of spontaneous resolution after birth." (PMID 21949750, 2011). "With the use of a microbubble ultrasound contrast agent and ultrasound-guided percutaneous aspiration, we demonstrated that antenatal hydronephrosis in Robo2-deficient mice is caused by high-grade VUR resulting from a dilated and incompetent ureterovesical junction rather than ureteral obstruction." (PMID 21949750, 2011). "In addition, our mouse model also informs us that we may uncover more deleterious mutations in ROBO2 gene if we focus on DNA analysis of patients with both progressive antenatal hydronephrosis and congenital high-grade dilating VUR." (PMID 21949750, 2011). "We recently showed that disruption of the Robo2 gene is associated with VUR in humans and antenatal hydronephrosis in knockout mice." (PMID 21949750, 2011). "After infusion of Option (a FDA-approved microbubble UCA) into the urinary bladder, we found that all (4/4, 100%) Robo2 mosaic mutant mice with hydronephrosis displayed VUR." (PMID 21949750, 2011). "The third evidence supporting a role for Robo2 in the anti-reflux mechanism is the golf-hole like ureteral orifice dilatation detected by both micro-ultrasonography and Hoxb7-GFP reporter gene in Robo2 mutant mice with hydronephrosis." (PMID 21949750, 2011). "Most Robo2 mosaic mutant mice develop antenatal hydronephrosis and abnormally located ureterovesical junctions (UVJs)." (PMID 21949750, 2011). "Perinatal genetic analysis for ROBO2 mutations might serve as an alternative to medical surveillance and watchful waiting, and may be used in the future as an early diagnostic tool to identify a subset of affected fetuses and newborns with progressive hydronephrosis and VUR." (PMID 21949750, 2011). "Interestingly, 25 (83%) of 30 Robo2 newborn mutant mice with hydronephrosis displayed wide open golf-hole like ureterovesical junctions and were confirmed by histology." (PMID 21949750, 2011). "With rapid maturation of mouse embryonic kidney and urinary tract from E16.5 to birth, bilateral and unilateral antenatal hydronephrosis and duplex kidneys in Robo2 mutant embryos could be diagnosed starting at E17.5–18.5." (PMID 21949750, 2011).
hydronephrosis (continued). "Although the hydronephrosis phenotype in Robo2 knockout mice has been attributed to the coexistence of ureteral reflux and obstruction in the same mice, this hypothesis has not been tested experimentally." (PMID 21949750, 2011). "We further documented Robo2 expression around the developing ureterovesical junction and identified early dilatation of ureteral orifice structures as a potential fetal origin of antenatal hydronephrosis and VUR." (PMID 21949750, 2011). "Therefore, the mosaic Robo2 genotype alone cannot predict the severity of hydronephrosis, and variable Robo2 gene dosage may be responsible for the broad-spectrum and variable severity of the CAKUT phenotype in Robo2del5/del5↔Robo2del5/flox mosaic mice." (PMID 21949750, 2011).
injury (1 paper, 2019). Damage inflicted on the body as the direct or indirect result of an external force, with or without disruption of structural continuity. "OPG, RGMB, and ROBO2 have been implicated in CNS development, axonal growth, and recovery after nerve injury, whereas upregulation of brevican has been observed in the CNS during the consolidation of long-term memories." (PMID 31694701, 2019).